C13orf46 (chromosome 13 open reading frame 46)
Gene: Protein-coding gene on chromosome 13 (113,953,705 to 113,974,076, reverse strand). Ensembl gene ENSG00000283199.
Homologues: Orthologues: macaque C17H13orf46 (82% identical), chimpanzee C13H13orf46 (81% identical), pig C13orf46 (58% identical), guinea pig C13orf46 (57% identical), mouse 1700029H14Rik (54% identical), rat C16h13orf46 (54% identical).
Diseases named in the same sentence as C13orf46 in open-access papers:
C13orf46 is named in the same sentence as 1 disease in open-access papers, as found by Europe PMC text mining. Sharing a sentence is not in itself a finding about the gene and the disease.
C13orf46 shares sentences with these, for which no sentence is quoted: cancer (1 paper).